MT1L (metallothionein 1L (pseudogene))
Description:
Metallothioneins have a high content of cysteine residues that bind various heavy metals; these proteins are transcriptionally regulated by both heavy metals and glucocorticoids.
Synonyms: MTF; MT1R; MT1LP; formerly MT1
Gene: Transcribed unprocessed pseudogene on chromosome 16 (56,617,563 to 56,618,680, forward strand). Ensembl gene ENSG00000260549.
Diseases named in the same sentence as MT1L in open-access papers:
MT1L is named in the same sentence as 16 diseases in open-access papers, as found by Europe PMC text mining. Sharing a sentence is not in itself a finding about the gene and the disease. The quoted sentences say what the papers report.
bladder cancer (2 papers, 2021 to 2022). "Another important finding was that MT1L is closely related to bladder cancer and is involved in its tumorigenesis, invasiveness, and recurrence, which suggests a potentially crucial biological functional role of MT1L in BLCA." (PMID 33888142, 2021). "Similarly, high expression of MT1L in bladder carcinoma predicted an unfavorable prognosis." (PMID 33888142, 2021).
colorectal cancer (2 papers, 2019 to 2021). A primary or metastatic malignant neoplasm that affects the colon or rectum. "MT1L is a pseudogene, and a previous study suggested that MT1L can be used as an indicator of prognosis in colorectal cancer." (PMID 33888142, 2021). "Collectively, these results indicate that high expression of MT1B, MT1H, or MT1L correlates with good prognosis in colorectal cancer patients." (PMID 31394742, 2019). "It has been confirmed that MT1L can be used as an indicator of prognosis in colorectal cancer." (PMID 33888142, 2021).
breast carcinoma (1 paper, 2022). "The roles of MT1CP, MT1L, and MT2A in HCC are still unknown, while MT2A could promote breast cancer invasiveness and might play a suppressive role in gastric cancer through inhibition of the NK-κB signaling pathway." (PMID 35300417, 2022).
chorioamnionitis (1 paper, 2022). A morphologic finding indicating inflammation of the fetal sac membranes. "The expression of MT1L was higher in the membranes in women delivering preterm in pregnancies complicated by chorioamnionitis." (PMID 36103557, 2022).
endometrial cancer (1 paper, 2023). Primary or metastatic malignant neoplasm involving the endometrium (mucous membrane that lines the endometrial cavity). "Having conducted a literature review, we found no previous studies on the relationship between the polymorphisms of MT1A (rs11076161), MT2A (rs28366003) and MT1L (rs10636) and the possibility of developing endometrial cancer." (PMID 36981043, 2023). "In our study, we decided to determine the presence of MT1A (rs11076161), MT2A (rs28366003) and MT1L (rs10636) polymorphisms among the studied patients as research on the influence of the selected polymorphisms on the risk of developing endometrial cancer has not yet been conducted." (PMID 36981043, 2023).
schizophrenia (1 paper, 2017). A major psychotic disorder characterized by abnormalities in the perception or expression of reality. "The paralogous genes of GBP1, MT2A and APOL1, including GBP2, MT1G, MT1E, MT1F, MT1L and APOLD1, were also upregulated in the schizophrenia cases." (PMID 28809853, 2017).
Tumor (3 papers, 2010 to 2021). "TIMER and TISIDB were used to demonstrate the association of MT1L with tumor-infiltrating immune cells." (PMID 33888142, 2021). "Also, the expression of MT1L was correlated with that of the markers of tumor-associated macrophages (TAMs) and M2 macrophages, especially the cell surface markers of M2-type macrophages." (PMID 33888142, 2021). "Tumor stage, Person neoplasm status, and MT1L expression level were verified to be independent prognostic factors." (PMID 33888142, 2021). "Collectively, these results reconfirmed that MT1L probably plays an integral correlative role in tumor immunity." (PMID 33888142, 2021). "In this study, we performed a series of analyses to evaluate the role of MT1L in the tumor immune response and assess its prognostic value in BLCA." (PMID 33888142, 2021). "Eventually, the results identified both the strong correlation between MT1L and the tumor immune system and the essential prognostic value of MT1L in BLCA." (PMID 33888142, 2021). "The function of metallothioneins in drug resistance has been well documented, and an earlier transcriptomic study of OS reported up-regulation of MTIG and MT1L in poorly responsive tumours." (PMID 20551950, 2010). "Therefore, the results from all three databases show that MT1L is an essential and unique factor in the tumor immune microenvironment, especially in BLCA." (PMID 33888142, 2021). "Similarly, the relationships between the expression levels of immune cell surface markers and MT1L imply the importance of MT1L in regulating the tumor immune microenvironment in BLCA." (PMID 33888142, 2021). "Thus, we suggest that MT1L has a potential influence on tumor immunology and plays a crucial role in regulating tumor immunity." (PMID 33888142, 2021).
cancer (2 papers, 2021 to 2022). A tumor composed of atypical neoplastic, often pleomorphic cells that invade other tissues. "We found genes related to extracellular matrix organization, such as SPP1, MT1L, and COL3A1 (among others), which functioned as NET-associated regulatory genes exclusively in cancer types with poor NET-related survival." (PMID 35432310, 2022). "MT1L is a pseudogene expressed in tissues of multiple cancers, including those of the brain, breast, thyroid, pancreas, etc.." (PMID 33888142, 2021). "In addition, analyses with R-4.0.2, GEPIA, Kaplan-Meier plotter, UALCAN, and GSEA methods verified the expression of MT1L in human cancers and demonstrated the role of MT1L in BLCA." (PMID 33888142, 2021). "Furthermore, it is obvious that the correlation between MT1L expression and TIL abundances was stronger in BLCA than in other human cancers." (PMID 33888142, 2021).
MT1L also shares sentences with these, for which no sentence is quoted: periodontal disease (2 papers); colon cancer (1); colorectal tumor (1); Down syndrome (1); gastric cancer (1); glaucoma (1); Hypertension (1); lung carcinoma (1).